ADORA2B (adenosine A2b receptor)
Diseases named in the same sentence as ADORA2B in open-access papers (continued):
Sharing a sentence is not in itself a finding about the gene and the disease.
colitis (4 papers, 2012 to 2022). Inflammation of the colon. "Currently, loss of ADORA2B is considered to result in down-regulation of IL10 production, with accentuation of colitis." (PMID 23638125, 2013). "Since previous studies had shown a protective role of Adora2b signaling during DSS colitis or intestinal ischemia and reperfusion, subsequent studies addressed the functional role of the Adora2b in netrin-1-elicited gut protection." (PMID 35910389, 2022). "Finally, we evaluated expression of HIF-1α and ADORA2B in intestinal mucosa from a rat animal TNBS-induced colitis model and evaluated the effect of 5-ASA." (PMID 23638125, 2013). "Pharmacologic targeting of adenosine pathways such as Adora2b may also synergize with modalities that activate the hypoxic response and have been shown to be tissue-protective in models of colitis." (PMID 22389701, 2012). "This concept was tested by creating an enteric glial-specific Adora2B ablation mouse model and studying the impact on inflammation and barrier dysfunction induced by dextran sulfate sodium (DSS) colitis." (PMID 35869148, 2022).
diabetes (4 papers, 2019 to 2025). "Most studies on the impact of diabetes on the expression and function of renal adenosine receptors have focused on the adenosine A2B receptor and showed overexpression." (PMID 31150459, 2019). "Emerging evidence highlights ADORA2B as a promising therapeutic target in numerous pathological conditions, including inflammatory processes, immune responses, ischemia–reperfusion injury, fibrosis, and diabetes mellitus." (PMID 40426853, 2025).
myocardial ischemia (4 papers, 2012 to 2024). A disorder of cardiac function caused by insufficient blood flow to the muscle tissue of the heart. "Adora2b also has a pronounced anti-inflammatory role in the context of ischemic tissue injury (i.e. transient tissue hypoxia) such that Adora2b-deficient mice have more severe acute ischemic injury in studies of both renal and myocardial ischemia." (PMID 22389701, 2012). "A specific agonist for Adora2b significantly reduced the size of infarct after myocardial ischemia." (PMID 36247475, 2022). "Studies using the HIF activator DMOG as a treatment approach for experimental myocardial ischemia showed that cardioprotection was eliminated in mice lacking Adora2b." (PMID 36247475, 2022).
atherosclerosis (3 papers, 2020 to 2023). A disease characterized by the build-up of fatty material and calcium deposition in the arterial wall resulting in partial or complete occlusion of the arterial lumen. "Disturbed lipid levels via modulation of ADORA2B also influenced the development of dyslipidemia and atherosclerosis, known risk factors of cardiovascular mortality." (PMID 32075205, 2020).
gastric cancer (3 papers, 2022 to 2025). A primary or metastatic malignant neoplasm involving the stomach. "This physiological role of Adora2b in regulating gastric acid secretion, however, is hijacked in the pathological setting of gastric cancer." (PMID 41346607, 2025). "Hypoxia, a hallmark feature of the gastric cancer microenvironment, coordinates three tumor-promoting processes—tumor cell adaptation, immune suppression, and metastasis—through the HIF-1α-Adora2b axis." (PMID 41346607, 2025). "Adora2b drives the formation of an immunosuppressive microenvironment in gastric cancer by regulating the functions of CD8+ T cells, regulatory T cells (Tregs), and tumor-associated macrophages (TAMs) through distinct downstream pathways." (PMID 41346607, 2025). "Recently, it was also shown that antagonizing Adora2b expression in gastric cancer cells increased the efficacy of cisplatin treatment." (PMID 37187740, 2023). "In early gastric cancer (Stages I-II), HIF-1α is expressed only minimally in the central tumor nests (occupying <15% of tumor cells), with a co-expression rate of 32% with Adora2b, failing to form a stable positive feedback loop." (PMID 41346607, 2025). "There is a great need to better understand the role of CD73 and Adora2b in gastric cancer, whether blocking adenosine signaling through inhibition of CD73 and/or Adora2a/Adora2b antagonism improves the potential for anti-tumor immunity in gastric cancer." (PMID 41346607, 2025). "In the gastric cancer (GC) tumor microenvironment (TME), tumors and stromal cells upregulate CD39/CD73, hijacking purinergic signaling to promote adenosine accumulation and activate Adora2b." (PMID 41346607, 2025).
myocardial infarction (3 papers, 2019 to 2022). Gross necrosis of the myocardium, as a result of interruption of the blood supply to the area, as in coronary thrombosis. "Collectively, APIP is crucial for cardioprotection against myocardial infarction by virtue of binding to and stabilizing ADORA2B, thereby dampening ischemic heart injury." (PMID 31263105, 2019). "Moreover, myocardial infarct areas in the hearts of Adora2b D296GKI/KI mice were significantly greater than those of age-matched WT mice." (PMID 31263105, 2019). "In addition, a recent study demonstrated a regulatory function for Adora2b signaling in promoting epicardial stromal cells′ HIF stabilization after myocardial infarction as an additional crosstalk between Adora2b and HIF implicated in cardioprotection after myocardial infarction." (PMID 36009485, 2022). "This suggests that, in response to myocardial infarction and reperfusion, activation of HIF1A coordinates cardioprotective effects by activating the expressions of Netrin-1 and ADORA2B, which both reduce post-ischemic myocardial inflammation." (PMID 36247475, 2022). "For example, Adora2b−/− mice are not protected by ischemic preconditioning and exhibit larger myocardial infarct sizes." (PMID 36009485, 2022). "Moreover, Adora2b D296G knock-in mice were more vulnerable than control mice to myocardial infarction and intentional increases in APIP levels overcame the defective protection of the ADORA2B SNP against ischemic injury." (PMID 31263105, 2019).
oral cancer (3 papers, 2015 to 2023). "ADORA2B is highly expressed in oral cancer, lung adenocarcinoma, and prostate cancer and promotes the proliferation and metastasis of carcinoma cells." (PMID 37760246, 2023). "Previous studies have demonstrated that ADORA2B participates in the proliferation and metastasis of carcinomas, such as prostate and oral cancers." (PMID 34350210, 2021).
pancreatic cancer (3 papers, 2023 to 2025). "Future studies will be needed to further demonstrate the potential role of Adora2b in pancreatic cancer metastasis as well as their potential impact on this and other diseases." (PMID 37187740, 2023). "Future studies using genetic models or orthotopic implantation of KPC cells into the pancreas will aid in further delineating the role of Adora2b in pancreatic cancer." (PMID 37187740, 2023). "Of the four receptors, Adora2a and Adora2b have been reported as high in PDAC and are overexpressed in the pancreas during pancreatic cancer; yet only high expression of Adora2b receptor was shown to correlate with significantly reduced survival in PDAC patients." (PMID 37187740, 2023).
Sepsis (3 papers, 2012 to 2025). Sepsis is defined as life-threatening organ dysfunction caused by a dysregulated host response to infection. "ADORA2B signaling is essential for mediating the anti-inflammatory effects of CXCR4/CXCR7 inhibition in peritonitis-associated sepsis." (PMID 41154678, 2025). "This balance between tissue-protection versus host-defense has been nicely revealed by studies of cecal ligation and puncture, in which Adora2b-deficient mice were more resistant to sepsis and sepsis-associated mortality." (PMID 22389701, 2012). "Previous experimental studies with mice and rats showed that sevoflurane reduced the PMN infiltration during acute peritoneal inflammation or polymicrobial sepsis through the Adora2b signaling." (PMID 35406657, 2022). "In line with our findings, previous studies demonstrated the impact of sevoflurane on migrated PMNs, tissue edema, and release of inflammatory chemokines in sterile and polymicrobial peritonitis and peritonitis-related sepsis by inducing the expression of Adora2b." (PMID 35406657, 2022).
sickle cell disease (3 papers, 2012 to 2024). Sickle cell anemias are chronic hemolytic diseases that may induce three types of acute accidents: severe anemia, severe bacterial infections, and ischemic vasoocclusive accidents (VOA) caused by sickle-shaped red blood cells obstructing small blood vessels and capillaries. "When studied the updated mechanisms underlying sickle cell disease-associated pain, it was discovered that ADORA2B factor can be used as a target gene to cause pain." (PMID 33494823, 2021). "For example, Adora2b signaling was recently revealed to be detrimental in sickle cell anemia, a context in which elevated levels of extracellular adenosine-Adora2b signaling promotes red blood cell sickling, contributing to the pathogenesis of this disease." (PMID 22389701, 2012). "Moreover, in sickle cell disease, the binding of adenosine to ADORA2B activates SPHK1, thereby increasing S1P production." (PMID 38426208, 2024).
acute respiratory distress syndrome (2 papers, 2021 to 2022). Progressive and life-threatening pulmonary distress in the absence of an underlying pulmonary condition, usually following major trauma or surgery. "Similarly, we also observed similar enhanced ADORA2B (3.33 ± 0.67 to 16.12 ± 5.89, p < 0.05) and decreased occludin (81.2 ± 0.3 to 13.3 ± 0.4, p < 0.05) levels in human Acute respiratory distress syndrome lungs." (PMID 33778007, 2021). "Studies of acute respiratory distress syndrome (ARDS), intestinal inflammation, myocardial or hepatic ischemia and reperfusion implicate the netrin-Adora2b link in tissue protection." (PMID 35910389, 2022).
breast tumor (2 papers, 2017 to 2022). "The expression of ABHD11, ADORA2B, E2F1, EZH2, PAICS, SFN and SH3GL1 was significantly higher in grade III than in grade I breast tumors." (PMID 28411283, 2017).
chronic kidney disease (2 papers, 2019 to 2025). Impairment of the renal function secondary to chronic kidney damage persisting for three or more months. "This process is activated by the adenosine A2B receptor (ADORA2B)‐S1P signaling cascade to mitigate hypoxia including high altitude, hemolytic disease, and chronic kidney disease." (PMID 39924931, 2025).
colon carcinoma (2 papers, 2015 to 2016). "ADORA2B was up-regulated consistently in colorectal carcinoma tissues and colon cancer cell lines compared with normal colorectal mucosa." (PMID 26228921, 2015).
colorectal cancer (2 papers, 2015 to 2024). A primary or metastatic malignant neoplasm that affects the colon or rectum. "Moreover, ADORA2B was overexpressed in colorectal carcinomas grown under hypoxic conditions." (PMID 26228921, 2015).
COVID-19 (2 papers, 2021 to 2024). A disease caused by infection with severe acute respiratory syndrome coronavirus 2. "We found 2 introns variants (rs4646120 and rs1978124) of ADORA2B which correlated with COVID-19." (PMID 33981715, 2021).
glioblastoma (2 papers, 2022). The most malignant astrocytic tumor (WHO grade IV). "Analysis of adenosine receptors showed that expression of ADORA2A/A2AR and ADORA2B/A2BR in glioblastoma and diffuse glioma were moderate compared to that of other cancers, while ADORA1/A1R and ADORA3/A3R were expressed at significantly higher levels in glioblastoma compared to all other tumor types." (PMID 35973991, 2022).
inflammatory bowel disease (2 papers, 2013 to 2015). A spectrum of small and large bowel inflammatory diseases of unknown etiology. "HIF-1α is a common transcription factor induced by ADORA2B activation in inflammatory bowel disease and urologic diseases." (PMID 26228921, 2015).
ischemia (2 papers, 2016 to 2018). A hypoperfusion of the BLOOD through an organ or tissue caused by a PATHOLOGIC CONSTRICTION or obstruction of its BLOOD VESSELS, or an absence of BLOOD CIRCULATION. "The selective antagonists of the adenosine A2B receptor subtype may thus represent a new class of neuroprotective drugs in ischemia." (PMID 29740323, 2018). "Furthermore, ischemia attenuated the CLP-induced increase in AdorA2b mRNA in left and right ventricles to about 52 and 58 % of values found for CLP, respectively." (PMID 27757725, 2016). "Therefore, we determined the effect of CLP on AdorA2a and AdorA2b mRNA expression in the right and left ventricle with or without ischemia." (PMID 27757725, 2016).
lung adenocarcinoma (2 papers, 2021 to 2023). A carcinoma that arises from the lung and is characterized by the presence of malignant glandular epithelial cells. "We investigated whether ADORA2B is a potential diagnostic and prognostic biomarker for lung adenocarcinoma (LUAD)." (PMID 34350210, 2021).
malaria (2 papers, 2010 to 2023). Malaria is a serious and sometimes fatal disease caused by a parasite that commonly infects a certain type of mosquito which feeds on humans. "The significant changes observed in the expression of ectonucleotidases and the adenosine receptors ADORA2a and ADORA2b in monocyte subsets, suggest a role for adenosine in malaria." (PMID 37545509, 2023).
pulmonary edema (2 papers, 2014 to 2021). Accumulation of fluid in the lung tissues causing disturbance of the gas exchange that may lead to respiratory failure. "A study by Eckle and colleagues also suggested that Adora2b promotes fluid clearance from the alveolus and attenuates pulmonary edema." (PMID 33778007, 2021). "Furthermore, loss of the ADORA2B had similar results with worsening of pulmonary edema following hyperoxia exposure without affecting inflammatory cell infiltration." (PMID 25263205, 2014).
acute kidney injury (1 paper, 2023). Sudden and sustained deterioration of the kidney function characterized by decreased glomerular filtration rate, increased serum creatinine or oliguria. "Signaling pathways involving the adenosine receptor encoded by Adora2b have been reported to exert protective effects during acute kidney injury by inhibiting neutrophil-dependent tumor necrosis factor-alpha release." (PMID 37125041, 2023).
allergic asthma (1 paper, 2021). A asthma with a basis in a pathological type I hypersensitivity reaction. "Selective ADORA2B antagonists have demonstrated anti-inflammatory effects in an allergic asthma mouse model, whereas combined agonism of ADORA2B and glucocorticoid receptors has been shown to induce transcription of anti-inflammatory genes in BEAS-2B cells, a human airway epithelial cell line." (PMID 35386996, 2021).
Arrhythmia (1 paper, 2021). Any cardiac rhythm other than the normal sinus rhythm. "The PPI k-means classification results suggested that 25 genes, iADORA1, ADORA2B, ADRA1A, ADRA1B, and ADRA1D, play a more important role in arrhythmia pathology and PRP treatment." (PMID 34393777, 2021).
astrocytoma (1 paper, 2012). "MAPKs have been reported to be involved in adenosine A2B receptor-mediated regulation of IL-6 gene expression in astrocytoma cells." (PMID 22894638, 2012).
brain tumors (1 paper, 2021). "Aiming at the development of a radiotracer labeled with the PET radionuclide fluorine-18 for imaging the adenosine A2B receptor in brain tumors, one of the most potent and selective antagonists, the xanthine derivative PSB-603, was selected as a lead compound." (PMID 34069548, 2021).
Burkitt lymphoma (1 paper, 2023). A rare form of malignant mature B-cell non-Hodgkin lymphoma. "Notably, the expression of Adora2a was considerably lower in PEL cells than in other cell lines examined, while the expression of Adora2b was elevated in most Burkitt lymphoma cell lines." (PMID 36786572, 2023).
cognitive decline (1 paper, 2025). "Intriguingly, recent mouse studies revealed that erythrocyte‐specific genetic ablation of Adora2b accelerates the early onset of age‐related hearing loss and cognitive decline." (PMID 39924931, 2025).
diabetic nephropathy (1 paper, 2020). "In these mice, CD73 levels in the kidney were elevated and genetic deletion of CD73 or the gene encoding ADO receptor, Adora2b, resulted in a more severe diabetic nephropathy." (PMID 32707842, 2020).
endothelial dysfunction (1 paper, 2024). In vascular diseases, endothelial dysfunction is a systemic pathological state of the endothelium (the inner lining of blood vessels) and can be broadly defined as an imbalance between vasodilating and vasoconstricting substances produced by (or acting on) the endothelium. "We also found dysregulation of angiogenesis genes (XDH, SEMA5A, and SULF1) and the Rap1 pathway (ADORA2B, GNAO1, SULF1, and EFNA2), which promotes endothelial homeostasis and may be involved in endothelial dysfunction-associated cardiovascular pathologies." (PMID 38255763, 2024).
head and neck squamous cell carcinoma (1 paper, 2021). A squamous cell carcinoma that arises from any of the following anatomic sites: lip and oral cavity, nasal cavity, paranasal sinuses, pharynx, larynx, and salivary glands. "ADORA2B knockdown reduced tumor vascularization and thus inhibited the growth of head and neck squamous cell carcinomas." (PMID 34925434, 2021).
heart failure (1 paper, 2019). Inability of the heart to pump blood at an adequate rate to meet tissue metabolic requirements. "Apaf-1-interacting protein (APIP) and ADORA2B transcript levels in human hearts are substantially higher in patients with heart failure than in controls." (PMID 31263105, 2019). "Interestingly, we observed similar expression patterns of APIP and ADORA2B in the hearts of patients with heart failure and of APIPTg/+ and APIP+/− mice." (PMID 31263105, 2019). "Given that the increased expression of APIP regulates ADORA2B level and protects the heart from MI, the increase of APIP as well as ADORA2B in the hearts of patients with heart failure is likely associated with signaling of cardioprotection during heart failure." (PMID 31263105, 2019). "Considering therapeutic potential, the ADORA2B D296G SNP or low level of ADORA2B in the heart of patients with heart failure would not respond well to the therapy employing an ADORA2B agonist." (PMID 31263105, 2019).
hepatoblastoma (1 paper, 2024). Hepatoblastoma (HB) is a malignant hepatic tumor and is the most common pediatric liver cancer. "In detail, we performed cell-line drug response and viability assays on the human HEPG2 hepatoblastoma cell line for CGS-15943, an ADORA2A and ADORA1 inhibitor, which is reported to act against multiple adenosine receptors, and MRS-1220, an ADORA3 and ADORA2B inhibitor." (PMID 38723607, 2024).
hepatocellular carcinoma (1 paper, 2011). A malignant tumor that arises from hepatocytes. "In order to further detect the function of A2bR, we established a stable hepatocellular carcinoma cell line (HepG2) expressing siRNA targeting the adenosine A2b receptor." (PMID 22091434, 2011). "Downregulation of adenosine A2b receptor gene expression with RNA interference could be a new approach to hepatocellular carcinoma therapy." (PMID 22091434, 2011).
Klebsiella pneumonia (1 paper, 2020). An pneumonia caused by infection with Klebsiella. "Mice with increased NET formation caused by a deficiency in the anti-inflammatory adenosine A2B receptor have been shown to have an enhanced capacity for bacterial clearance from the lungs and increased survival when challenged with Klebsiella pneumonia." (PMID 32265910, 2020).
lung diseases (1 paper, 2021). "Moreover, the data suggesting ADORA2B and CD73 as potential therapeutic targets may be more efficacious in improving chronic CS lung diseases and impaired wound repair." (PMID 33584346, 2021).
maturity onset diabetes (1 paper, 2022). "For KEGG pathway enrichment results, folate biosynthesis, maturity onset diabetes of the young, olfactory transduction, sulfur metabolism as well as taurine and hypotaurine metabolism were positively linked to ADORA2B." (PMID 36506308, 2022).